INS (insulin)
Diseases named in the same sentence as INS in open-access papers (continued):
Sharing a sentence is not in itself a finding about the gene and the disease.
Hypoglycemia (continued). "If the patient is not hypoglycemic when observed, the association of severe hypoglycemia with non-suppressed insulin levels should be seeked under the conditions in which hypoglycemia would be expected (see provocative testing, “Spontaneous hypoglycemia”)." (PMID 25038902, 2014). "The results of the present study demonstrated that during the intervention period, the incidence of hypoglycemia was significantly higher in the insulin-glargine group as compared with the standard-care group, however, the risk of cardiovascular events was similar between the two groups." (PMID 24944613, 2014). "Furthermore, an experimental physiological increase in insulin concentrations for the final week of chronic fetal hypoglycemia resulted in normalization of the expression of the ubiquitin ligases." (PMID 24944291, 2014). "In one study intensified insulin therapy reduced the mortality of critically ill hyperglycaemic surgical patients, although this strategy led to frequent severe hypoglycaemia in patients with bacterial sepsis and increased mortality in a general ICU population." (PMID 24489828, 2014). "It is widely accepted that insulin promotes severe hypoglycaemia and weight gain." (PMID 24752580, 2014). "In this aspect, many previous studies have reported the efficacy and safety of combination therapy of oral hypoglycemic agents (OHAs) and insulin, indicating advantages such as the reduction of the insulin dose, the prevention of weight gain or hypoglycemia, and the improvement of glycemic control." (PMID 27419209, 2014). "Fear of hypoglycemia may lead to preventive coping behaviors, such as taking less insulin or increasing food intake, that negatively affect glycemic control." (PMID 25433668, 2014). "During hypoglycemia the most insulin resistant subjects increased their MGU." (PMID 24400077, 2014). "Significant predictors of having a depressive mood included female gender, single marital status, current and past smoking status, lack of physical activity, higher BMI and total cholesterol level, increased number of comorbidities, history of hypoglycemia, and insulin treatment." (PMID 25431771, 2014). "These neurons are clearly activated by insulin-induced hypoglycemia; however whether this is simply because they are GI neurons or whether insulin is having an independent effect is not known." (PMID 25540613, 2014). "During insulin therapy, one of the most common adverse reactions is hypoglycemia." (PMID 24790575, 2014). "Assays with C. citratus aqueous extract (500 mg/kg/day; via oral) showed that the mechanism by which the extract induced hypoglycemia could be attributed to increased insulin synthesis and secretion or increased peripheral glucose utilization." (PMID 25574396, 2014). "However, the most common complications of DKA include hypoglycemia due to overzealous insulin treatment, hypokalemia due to insulin administration, and bicarbonate treatment of acidosis." (PMID 25184062, 2014). "The reasons for this remain uncertain, but we suggest that combination therapy of metformin plus glimepiride with add-on therapy of insulin glargine lead a decrement of insulin doses without differential increase in the risk of hypoglycemia." (PMID 24614911, 2014). "The cognitive alterations that can occur during hypoglycemia are not caused by the increased release of glucagon, adrenalin, noradrenalin, GH, and cortisol nor even by excess insulin." (PMID 24790575, 2014). "Chronic experimental restriction of glucose transfer to the sheep fetus for the final 40% of gestation with a maternal insulin infusion (HG fetuses) results in fetal hypoglycemia, hypoinsulinemia, and decreased rates of fetal growth and protein accretion compared to controls (CON)." (PMID 24944291, 2014). "Insulin-induced hypoglycemia is a stressor that produces large increases in plasma CRF and ACTH." (PMID 24616659, 2014).
Hypoglycemia (continued). "In a retrospective study by Arabi and colleagues, glucose intake was not a risk or protective factor of hypoglycemia whereas insulin daily dosage was an evident risk factor (73.5 ± 36.7 in the group presenting hypoglycemia versus 47.5 ± 51.8; P < 0.0001)." (PMID 25177798, 2014). "Finallyt, as already described, the development of hypoglycemia in porcine endotoxic shock could be due to a peak in the insulin level at 90 minutes." (PMID 25125153, 2014). "A possible explanation for post-load hypoglycemia may have been differences in insulin concentrations, but we noticed similar insulin and C-peptide responses to the oral glucose load in patients with hypoglycemia and patients with euglycemia." (PMID 24736741, 2014). "These might be largely affected by frequent episodes of severe hypoglycaemia and weight gain with intensive insulin therapy." (PMID 24607023, 2014). "The combination of renal dysfunction and insulin use put patients at high risk for hypoglycaemia if they were not monitored closely." (PMID 24927961, 2014). "Because data in the CF ferret model suggests the potential for impaired shutoff of insulin secretion during hypoglycemia, we also developed a clamp protocol capable of assessing the kinetics of insulin reductions following the transition from a hyperglycemic to a hypoglycemia state." (PMID 24594704, 2014). "This study could be used as a guidance for larger studies to investigate the effects of this intervention on insulin requirements, glycemic variability, hypoglycemia and weight gain." (PMID 25175981, 2014). "Also, the incidence of severe hypoglycemia is reported to be higher in geriatric patients compared with younger patients when treated with insulin alone." (PMID 23959960, 2014). "Compared with conventional blood glucose control, blood glucose control by using an artificial pancreas in postoperative patients was reported to reduce the incidence of hypoglycemia, dose of insulin administered, days of hospital stay, and incidence of infection in single-center studies." (PMID 25705413, 2014). "Use of these devices thus may increase the timeliness and safety of insulin initiation and up-titration among people with T2D, particularly by identifying asymptomatic nocturnal hypoglycemia and unrecognized post-prandial glucose elevations." (PMID 24886287, 2014). "Following emergency treatment of hypoglycemia, an α-glucosidase inhibitor may be prescribed in combination with dietary control to decrease endogenous insulin secretion." (PMID 25289063, 2014). "In addition, ITT has been shown to increase c-fos expression in lateral hypothalamic orexinergic neurons, which is coupled to an increase in activity of these neurons, suggesting that insulin-induced hypoglycemia is able to robustly activate the orexin system." (PMID 24770625, 2014). "While performing insulin therapy, it is crucial to prevent hypoglycemia." (PMID 25278226, 2014). "Serum total IRI and free insulin levels were significantly increased disproportionately, which indicated that hypoglycemia may be secondary to MTZ-induced IAS." (PMID 25289063, 2014). "Earlier studies demonstrated that factors like old age, long disease duration, poor renal function, peripheral neuropathy, low body mass index (BMI), ≥2glucose-lowering drugs, long duration of insulin treatment, etc. are significant independent predictors of hypoglycemia." (PMID 24528773, 2014). "Glycemic variability may be a unique patient attribute, it may be the result of unnecessary inter-physician variation while attempting to control blood sugar with insulin, or it may be a consequence of hypoglycemia, believed to confer harm." (PMID 24886864, 2014). "Often considerable doses of insulin are needed and weight gain and hypoglycemia can occur." (PMID 25175981, 2014).
Hypoglycemia (continued). "This study demonstrated that combination therapy with bedtime insulin plus metformin prevents weight gain and this regimen also seems superior to other bedtime insulin regimens with respect to improvement in glycemic control and frequency of hypoglycemia." (PMID 24614911, 2014). "In the non-insulin using sample, all negative items except for item 7 (‘increases risk of hypoglycaemia’), loaded onto the factor and in the insulin using sample only item 9 (‘weight gain’) did not load." (PMID 24902877, 2014). "However, blood glucose measurement by glucose meters using capillary blood are inaccurate and tend to be estimated higher, leading to inappropriate insulin infusion, then occurrence of hypoglycemia." (PMID 25705413, 2014). "In addition, adverse effects of insulin therapy, such as weight gain and hypoglycemia are problematic." (PMID 25302493, 2014). "Intensive insulin therapy, however, notably increased the episodes of hypoglycemia." (PMID 25136614, 2014). "The quick lowering effect on blood glucose as well as the super tolerance to glucose challenge in anti-CD3 treated mice suggests that anti-CD3 treatment might have enhanced β cell function in secreting insulin thereby leading to hypoglycemia." (PMID 24741590, 2014). "Moreover, there is limited information available regarding therapeutic options for patients for who premixed insulin provides inadequate glycemic control, who frequently experience episodes of hypoglycemia or those who want to avoid additional injections." (PMID 24620742, 2014). "Recurrent episodes of unexplained hypoglycemia necessitated measurement of insulin levels by using different insulin assays, which revealed hyperinsulinemic hypoglycemia with low C-peptide levels, findings which confirmed a diagnosis of factitious hypoglycemia." (PMID 25541899, 2014). "To examine whether GKA23 treatment induced persistent insulin secretion during hypoglycemia, we performed a hypoglycemic clamp study using low dose exogenous insulin levels infusion." (PMID 24533087, 2014). "This surge of plasma insulin level could be the result of metabolic compensation occurred after fasting in response to hypoglycemia." (PMID 24891878, 2014). "Higher incidence of neonatal hypoglycemia and macrosomia may be the result of even minimal transfer of drug, which might have increased insulin release from fetal beta cells." (PMID 25302493, 2014). "Modulation of male PVH gene expression in response to hypoglycemia is rapid and apparent within 60 minutes of insulin injection; interestingly this is within the time frame of previously observed glucose-sensitive AMPK- and CREB coactivator-mediated transcriptome changes." (PMID 24684305, 2014). "The results of the present observational study explore the incidence and predictors of hypoglycemia in real-life clinical practice in insulin-naïve diabetic patients in Japan having inadequate glycemic control and who are starting with BOT with insulin glargine." (PMID 24528773, 2014). "In addition, insulin-induced hypoglycemia or neuroglucoprivation induces Fos expression in orexin neurons of the PeH suggesting a possible role in glucose sensing." (PMID 24616659, 2014). "However, a physiological increase in fetal insulin after prolonged fetal hypoglycemia further reduced circulating fetal mannose concentrations, indicating that insulin also plays a key role in regulating mannose concentrations." (PMID 24917928, 2014). "In addition to hypoxia and intermittent hypoxia, insulin was found recently to be a regulator of the CB response to hypoglycemia." (PMID 25360117, 2014). "This study could be used as a guidance for larger studies that are required to investigate the effects of this intervention on insulin requirements, glycemic variability, hypoglycemia and weight gain." (PMID 25175981, 2014). "GLP-1 preserves MGU during hypoglycemia in insulin resistant subjects." (PMID 24400077, 2014).
Hypoglycemia (continued). "Higher income, white race, and treatment without sulfonylurea or insulin were associated with less hypoglycemia fear (all P < 0.05)." (PMID 25433668, 2014). "Severe hypoglycemia occurs very frequently in patients submitted to insulin therapy." (PMID 24790575, 2014). "In our patient, the symptoms of hypoglycemia occurred 2–3 h postprandially, as a large number of insulin molecules released after food ingestion may bind to these low-affinity/high-capacity IABs, which prevent insulin from acting." (PMID 25289063, 2014). "In contrast, insulin therapy results in large spikes in blood glucose (as also seen in βV59M mice), because an insulin dose sufficient to fully control meal-stimulated spikes in plasma glucose cannot be used, as it would produce hypoglycaemia at fasting plasma glucose levels." (PMID 25145789, 2014). "However, premixed insulin alone can be insufficient to achieve and sustain optimal glycemic control, and there are often additional concerns regarding hypoglycemia, weight gain, and lifestyle restrictions." (PMID 24620742, 2014). "GLP-1 increases insulin and decreases glucagon secretion in a glucose-dependent manner, resulting in low incidence of hypoglycaemia, which is a major advantage in the perioperative period and may reduce workload, thereby improving compliance." (PMID 25419179, 2014). "Indeed, hypoglycemia induced by the overdose of insulin therapy or oral anti‒diabetic agents was observed in five patients, and almost all of the diabetic patients had experienced recurrent hypoglycemic episodes." (PMID 25520819, 2014). "Fear of hypoglycemia remains one of the key barriers to initiating and optimizing insulin therapy." (PMID 24092662, 2014). "Hypoglycemia is a severe side effect of intensive insulin therapy." (PMID 23894333, 2013). "GLP-1 agonists are as effective as insulin at reducing HbA1c, with the additional benefit of weight loss without hypoglycemia, but then a proportion of cases develop nausea and acute pancreatitis is, possibly, an additional, albeit very small, risk." (PMID 23841986, 2013). "The potential for GLP-1 RAs to lower glucose concentrations without increasing the risk for hypoglycaemia when used in combination with insulin is one of the regimen's most attractive features." (PMID 23061470, 2013). "Thus, following a transitory burst of ROS and NO production in response to a single episode of insulin-hypoglycemia, VMH S-nitrosylation level remains increased for some time." (PMID 23894333, 2013). "In the UKPDS 16% of SU and 36% of insulin treated patients experienced hypoglycemia." (PMID 23574917, 2013). "In contrast, the increased amount of insulin present in the circulation will reduce or even prevent the mobilization of glucose which can result in hypoglycemia; it may explain the weaker results of physical fitness of the group with T1D." (PMID 23935617, 2013). "During an episode of hypoglycaemia (1.2 mmol/l), his insulin level was 11.7 mU/l." (PMID 24616771, 2013). "Although hypoglycaemia rates are naturally higher when treating with insulin, the marked improvements in efficacy and, in the case of IDeg, the possibility of flexibility with regard to dose timing when needed, support the benefits of earlier initiation of basal insulin in relevant patient groups." (PMID 23577643, 2013). "This gives a more accurate pattern of daily glucose fluctuations allowing identification of the glycemic effect of food, physical activity, insulin and different medication types and doses aiding in better self management with avoiding unrecognized hypoglycemia." (PMID 23876067, 2013). "Different pump conditions for regulating insulin release may also contribute to different incidence rates of hypoglycemia." (PMID 24223662, 2013). "Acute insulin-hypoglycemia increased VMH ROS levels by 49±6.3%." (PMID 23894333, 2013).
Hypoglycemia (continued). "Since CHI is characterized by severe hypoglycemia due to inappropriate insulin secretion from pancreatic β-cells, we hypothesized that mutations in genes involved in this process might be responsible for the disease." (PMID 23869231, 2013). "The lower rate of hypoglycaemia with insulin detemir may in part be attributable to its lower within-subject variability compared with NPH." (PMID 23094597, 2013). "The main side effects of insulin include weight gain and hypoglycemia." (PMID 24260037, 2013). "Weight gain was reportedly low and similar across all three treatment groups, whereas the rates of confirmed symptomatic hypoglycaemia were 12.2, 12.9 and 17.1 events/person-year in the insulin glulisine once-, twice- and three-times-daily groups, respectively." (PMID 22998363, 2013). "Mice with hypoglycemia display diminished insulin release in response to elevated glucose." (PMID 23977255, 2013). "During hypoglycemia, insulin secretory rates declined similarly and rapidly in both groups." (PMID 23256660, 2013). "Hence, attempting to minimize the occurrence of hypoglycaemia in children is essential, and it is therefore noteworthy that there were fewer severe hypoglycaemic events with insulin detemir than with NPH." (PMID 23094597, 2013). "The fall in HbA1c comes at a cost of rising hypoglycemia-risk, and analogues of long-acting and short-acting insulin reduce nocturnal hypoglycemia and post-prandial glucose, respectively, without benefiting HbA1c levels." (PMID 23841986, 2013). "In addition, birds appear insulin insensitive, with blood glucose levels either unaffected by exposure to insulin or with moderate hypoglycemia induced only by exposure to supra-physiological insulin levels." (PMID 24155916, 2013). "In both type-2 and type-1 diabetes, long term preservation of β-cell function has been shown to improve long term glycemic control, improve the response to medications (including insulin), reduce the frequency of treatment-related hypoglycemia, and diminish complications." (PMID 23408938, 2013). "In addition to hypoglycemia, inappropriate weight gain following treatment with insulin is a major barrier to achieving glycemic control in teenagers and adults with T1D." (PMID 23448369, 2013). "The insulin levels although decreasing were perhaps sufficiently high enough during hypoglycaemia to suppress the counterregulatory response which may have resulted in the glucose levels remaining low." (PMID 23424590, 2013). "In summary, our data demonstrate a marked reduction in gluconeogenic substrate-driven glucose production in the liver of the FynKO mice, which functions in metabolic concert with enhanced peripheral tissue insulin sensitivity and fatty acid oxidation and results in fasting hypoglycaemia." (PMID 24312371, 2013). "However, insulin therapy can induce adverse effects, however, including modest weight gain and hypoglycemia." (PMID 23874448, 2013). "In contrast, GLP-1 RAs, when used without insulin secretagogues do not increase the risk for hypoglycaemia because of the glucose-dependent nature of their stimulation of insulin release (e.g. 23)." (PMID 23061470, 2013). "This study has retrospectively evaluated associations between hypoglycaemia and accident risk among people receiving antidiabetes drugs (without insulin) in a large American claims database." (PMID 23121373, 2013). "Hypoglycaemia and the fear of hypoglycaemia are barriers to achieving normoglycaemia with insulin." (PMID 23130654, 2013). "Subject 2 has insulin autoantibodies (IAA) associated with hypoglycemia in spite of not being diabetic and not having ever received exogenous insulin therapy." (PMID 24386337, 2013). "Hypoglycaemia is a frequent finding resulting from inadaequate insulin dosing in T1D." (PMID 24053606, 2013). "It is well accepted that insulin-induced hypoglycemia can result in seizures." (PMID 24386156, 2013).